PCSK9 (proprotein convertase subtilisin/kexin type 9)
Diseases named in the same sentence as PCSK9 in open-access papers (continued):
Sharing a sentence is not in itself a finding about the gene and the disease.
viral infections (27 papers, 2017 to 2026). "Other members of the PCSK-family are also implicated in some viral infections, such as PCSK9 in Dengue." (PMID 34202098, 2021). "It has been suggested that increased circulating PCSK9 might be associated with different bacterial and viral infections and that inhibiting the activity of circulating PCSK9 levels using PCSK9 inhibitors may be useful for the treatment of bacterial sepsis and septic shock." (PMID 31635200, 2019). "Beyond its effects on LDL, recent studies have reported pleiotropic effects of PCSK9, notably in septic shock, vascular inflammation, viral infection, and cancer." (PMID 40338666, 2025). "The promising beneficial effects of inhibitory PCSK9 antibodies and other cholesterol-depleting drugs, which protected from viral infection in preclinical studies, have yet to be validated in patient cohorts." (PMID 38388172, 2024). "While PCSK9's lipid-regulating function is universally acknowledged, its multifaceted functions extend to inflammation, gastrointestinal diseases, and viral infections." (PMID 38341813, 2024). "The role of PCSK9 in viral infections is just emerging, as exemplified by upregulated expression of PCSK9 during dengue virus infection leading to a reduced innate immune response to the virus." (PMID 36851576, 2023). "Recent studies uncovered more biological functions of PCSK9, including vascular inflammation, viral infections, or immune checkpoint modulation in cancer." (PMID 37898598, 2023). "Our data characterizes PCSK9 as a possible, clinically relevant biomarker for viral infections, and this should be further evaluated in multi-center studies." (PMID 37515197, 2023). "Considering the fact that the pathogenesis of viral infections involves many host factors, e.g., lipids and lipoproteins, the influence of PCSK9 inhibitors on the course of viral infections has captured the attention of many scientists all over the world." (PMID 35323699, 2022). "The three patients with viral disease etiology had higher PCSK9 plasma levels in SVP (P = 0.015), HVP (P = 0.016) and PVP (P = 0.014) than patients with alcoholic liver cirrhosis." (PMID 33461570, 2021). "We further examined the PCSK9 protein level at various time points in MARC-145 cells that were transfected with PCSK9 followed by HuN4 virus infection." (PMID 32560445, 2020). "Therefore, conducting more large-scale and well-organized clinical studies will be essential to corroborate and advocate for the further application of PCSK9-iTs in the management of viral infections in the future." (PMID 38185721, 2024). "Extracellular PCSK9 enhanced ACE2 degradation and vice versa: low PCSK9 levels may be related to higher ACE2 levels, which have anti-inflammatory activities but have also been associated with increased virus infection." (PMID 39408818, 2024). "Our results suggest that high levels of metalloproteases and PCSK9 may protect against viral infection by enhancing the shedding of S-glycoprotein and the degradation of ACE2, respectively." (PMID 36851576, 2023). "PCSK9 inhibitors may inhibit viral infection by reducing viral cholesterol levels, such as dengue virus, according to some previous virus related studies." (PMID 38093957, 2023). "PCSK9 also has positive functions including liver regeneration, protection against viral infections, and brain development, which could lead to serious side effect when this convertase is inhibited." (PMID 32587953, 2020). "So far, it has not been possible to explicitly confirm or contradict that PCSK9 is directly involved in the pathogenesis of viral diseases." (PMID 35323699, 2022).
viral infections (continued). "Interestingly, PCSK9 protein levels were increased in the liver of HCV patients when compared to patients with nonviral liver disease, indicating that viral infection may contribute to influencing the machinery responsible for PCSK9 expression and secretion." (PMID 35162992, 2022).
psoriasis (26 papers, 2019 to 2024). An autoimmune condition characterized by red, well-delineated plaques with silvery scales that are usually on the extensor surfaces and scalp. "A study led by Merleev identified a potential locus at 1p32.3, associated with psoriasis susceptibility, situated within PCSK9 (rs662145 C > T)." (PMID 38185721, 2024). "Several studies exploring the link between PCSK9 and psoriasis have pinpointed the protein as a potential contributor to psoriasis susceptibility and progression." (PMID 38185721, 2024). "By means of RNA-Seq-based variant detection, the authors uncovered a potential psoriasis susceptibility locus at 1p32.3 within the gene PCSK9 (rs662145)." (PMID 36980866, 2023). "Only one clinical study explored the therapeutic effect of PCSK9 inhibitors (e.g., alirocumab) on psoriasis, and the results showed that inhibition of PCSK9 was associated with a reduced psoriasis risk." (PMID 37234169, 2023). "Using RNA-Seq–based variant discovery, we identified a possible psoriasis-susceptibility locus at 1p32.3, located within PCSK9 (rs662145 C > T)." (PMID 35862195, 2022). "This was established by mining psoriasis and healthy control RNA-Seq data sets for differential occurrences of PCSK9 variants." (PMID 35862195, 2022). "Together, these results support PCSK9 as a psoriasis-susceptibility locus and establish a putative link between PCSK9 and inflammatory cytokine expression." (PMID 35862195, 2022). "We show that an SNP at the 3′ untranslated region of PCSK9 (rs662145 C > T) predisposed individuals to psoriasis, a finding that was verified in independently acquired psoriasis RNA-Seq and genomic data sets." (PMID 35862195, 2022). "To further confirm the association between PCSK9 SNP rs662145 C > T and psoriasis, we next examined the 1p32.3 genomic region in 2590 patients with psoriasis and 1720 controls, using data from previously published and recently acquired data sets." (PMID 35862195, 2022). "After considering these data, we maintained the thesis that PCSK9 seems to play a role in psoriasis and its association with the proatherogenic lipid profile, however further investigations are needed." (PMID 32225075, 2020). "To conclude, our study for the first time showed that PCSK9 levels are significantly increased in psoriatic patients and seems to be a novel marker of psoriasis and risk assessment of cardiometabolic disorders in this dermatosis." (PMID 32225075, 2020). "Another recently published study found that the PCSK9 single nucleotide polymorphism (SNP) rs662145 was a psoriasis susceptibility locus and that PCSK9 expression is negatively linked to IL-36, a critical driver of psoriasis." (PMID 37234169, 2023). "Thus, in multiple independent data sets, PCSK9 rs662145 C > T was associated with an increased risk of psoriasis." (PMID 35862195, 2022). "The major finding of our study is the identification of PCSK9 as a psoriasis-susceptibility locus." (PMID 35862195, 2022). "Given that patients on PCSK9 inhibitors have been reported to develop various inflammatory skin eruptions, we used RNA-Seq–based genetic variant discovery to mine the largest published psoriasis transcriptome data set for SNPs of PCSK9." (PMID 35862195, 2022). "Serum PCSK9 levels had a strong correlation to BMI and triglyceride levels, indicating that PCSK9 could be a novel marker for psoriasis and associated cardiovascular risks in psoriatic patients." (PMID 35682804, 2022). "Here, we explore PCSK9 as a possible psoriasis-susceptibility locus." (PMID 35862195, 2022). "Although PCSK9 SNPs (e.g., rs662145 C > T) have been linked to cardiovascular disease and Alzheimer’s disease, their association with psoriasis remains unknown." (PMID 35862195, 2022). "Although gaps in our understanding of these relationships remain, our working hypothesis is that PCSK9 SNP rs662145 C > T may predispose individuals to psoriasis by increasing baseline cutaneous expression of IL36G." (PMID 35862195, 2022).
psoriasis (continued). "We then investigated whether PCSK9 is linked to other potential inflammatory mediators of psoriasis in addition to IL36B and IL36G." (PMID 35862195, 2022). "To further assess how PCSK9 expression was associated with other keratinocyte-expressed psoriasis-relevant genes, we created a 2-dimensional plot of the keratinocyte transcriptome using the t-Distributed Stochastic Neighbor Embedding (t-SNE) dimensionality reduction method." (PMID 35862195, 2022). "Psoriasis-linked PCSK9 variant rs662145 C > T is associated with altered PCSK9 and IL36 expression." (PMID 35862195, 2022). "We next aimed to establish if PCSK9 expression was linked to any well-known mediator of psoriasis." (PMID 35862195, 2022). "Furthermore, PCSK9 genotyping data from 2590 psoriasis cases and 1720 controls also associated the exact same SNP, rs662145 C > T, to the psoriasis phenotype (P = 2.6 × 10–4)." (PMID 35862195, 2022). "Additionally, various reports have linked PCSK9 with systemic lupus erythematosus, rheumatoid arthritis, psoriasis, systemic sclerosis, and nephrotic syndrome." (PMID 33925815, 2021). "Moreover, NAFLD, which is closely linked to psoriasis morbidity, increases circulating PCSK9 concentrations, which in turn correlate positively with hepatic fat accumulation, irrespectively of other metabolic factors." (PMID 32456228, 2020). "This inverse relationship provides a plausible explanation as to how PCSK9 SNP rs662145 C > T may predispose individuals to psoriasis — i.e., lowering PCSK9 expression in keratinocytes increases baseline cutaneous expression of IL-36, a psoriasis-driving cytokine." (PMID 35862195, 2022). "In addition to identifying PCSK9 as a psoriasis-susceptibility locus, we performed the initial studies to understand how the psoriasis-linked PCSK9 variant, SNP rs662145 C > T, might predispose individuals to psoriasis." (PMID 35862195, 2022). "Furthermore, the PCSK9 inhibitor evolocumab, which is approved for the treatment of hypercholesterolemia, has been associated with the development of various inflammatory skin conditions including psoriasis." (PMID 35862195, 2022). "Thus, while homozygosity for the psoriasis-linked PCSK9 variant rs662145 C > T was consistently associated with lower PCSK9 expression and higher IL36G expression, homozygosity for the PCSK9 reference allele appeared to yield different results in vitro and in vivo." (PMID 35862195, 2022). "After identifying PCSK9 as a possible psoriasis-susceptibility locus, we next sought to determine how the psoriasis-associated PCSK9 variant, rs662145 C > T, may predispose individuals to psoriasis." (PMID 35862195, 2022). "In the development of these autoimmune diseases, such as SLE, RA, and psoriasis, PCSK9 levels are strongly correlated with disease activity and severity." (PMID 39736777, 2024). "further found that the level of PCSK9 was higher in psoriasis patients and K14-Rac1V12 -/+ psoriatic mice and was positively linked with the severity of psoriasis." (PMID 37234169, 2023). "Circulating PCSK9 showed previously strong correlation with severity of imiquimod model of psoriasis in mice but only moderate correlation with PASI (r = 0.43) in human psoriasis." (PMID 37763277, 2023). "The concentration PCSK9 in serum was previously found to be significantly increased in both human patients with psoriasis and murine model of psoriasis." (PMID 37763277, 2023). "Serum level of NGAL shows moderate to strong correlation with BSA and PASI, respectively, whereas PCSK9 remains independent on the severity of psoriasis, but it correlates with the levels of TChol and LDL in serum." (PMID 37763277, 2023). "Examining PCSK9 expression in cultured keratinocytes revealed that SNP rs662145 C > T was associated with differential expression of IL36, an IL-1 family member and psoriasis-defining cytokine." (PMID 35862195, 2022).
psoriasis (continued). "The study, involving two separate human psoriasis cohorts, showed increased levels of PCSK9 in psoriatic patients compared to age-, sex-, and cholesterol-matched controls." (PMID 35682804, 2022). "Genetic deletion of PCSK9 or topical application of siRNA targeting PCSK9 relieved the psoriasis-like inflammation as well as the proliferation of keratinocytes." (PMID 35075118, 2022). "In an imiquimod mouse model of psoriasis-like dermatitis, suppressing PCSK9 with siRNA resulted in improvement of skin lesions." (PMID 35862195, 2022). "Patients with psoriasis present reduced levels and efflux capacity of HDL-C, increased LDL-C particle concentration and decreased LDL-C size, as well as elevated levels of circulating PCSK9 when compared to non-psoriasis individuals." (PMID 35755028, 2022). "There is also evidence for the eminent role of the PCSK9 in the psoriasis and cardiometabolic syndrome linkage." (PMID 34445769, 2021). "Psoriatic patients showed significantly elevated levels of PCSK9 compared to controls (p < 0.01), mostly in patients with a mild and moderate course of psoriasis." (PMID 32225075, 2020). "So far, in our previous study, we proved that PCSK9 has to be considered a novel biomarker of psoriasis, and further, we have proven that methotrexate should be the treatment of choice in patients with an elevated PCSK9 concentration before treatment." (PMID 32456228, 2020). "Based on the available literature’s data, our study is the first one assessing serum PCSK9 concentrations in patients with psoriasis and evaluating the impact of conservative and well-established treatments." (PMID 32225075, 2020). "In that paper, the authors examined the potential of topically applying small interfering RNA targeting PCSK9 as the psoriasis treatment using murine and cell culture models." (PMID 32456228, 2020). "Accordingly, to the severity of psoriasis after treatment, PCSK9 remained significantly increased in all PASI sub-groups versus the controls." (PMID 32225075, 2020). "To conclude, accumulated data suggest that PCSK9 plays a crucial role in psoriasis, promoting the occurrence of its comorbidities and it should be considered as an important and effective therapeutic target." (PMID 32456228, 2020). "Our previous study reported that suppressing PCSK9 inhibited the hyper-proliferation of keratinocytes and reduced the psoriasis-like inflammation via the NFκB pathway." (PMID 31824416, 2019). "Their research found that psoriasis patients and IMQ-treated mice both had elevated PCSK9, and that inhibiting PCSK9 could lessen the inflammatory response in psoriasis by inhibiting KCs proliferation and the NF-κB pathway." (PMID 37234169, 2023). "Recent studies showed that PCSK9 takes part in the development of psoriasis." (PMID 37234169, 2023). "Furthermore, PCSK9, in the past few years, has also been recognized as a potential psoriasis trigger and co-factor promoting psoriasis comorbidities." (PMID 36980866, 2023). "Inhibition of PCSK9 was associated with a lower risk of psoriasis, whereas inhibition of HMGCR and NPC1L1 did not have an impact." (PMID 37964871, 2023). "Proprotein convertase subtilisin-kexin type 9 (PCSK9) is a sensitive gene in psoriasis, and its protein is elevated in the skin lesions and serum of psoriasis patients; knockout of PCSK9 slows the development of psoriasis-like skin lesions and inflammation in mice." (PMID 37762693, 2023). "Similarly, the expression patterns and role of PCSK9 in human keratinocytes in healthy individuals and patients with psoriasis are uninvestigated." (PMID 35862195, 2022). "In summary, our study establishes PCSK9 as a possible psoriasis-susceptibility locus and demonstrates its negative relationship with IL36G at the gene expression and protein levels." (PMID 35862195, 2022). "Together these results link PCSK9 to psoriasis and inflammatory cytokine production in human skin." (PMID 35862195, 2022).